BDNF (brain derived neurotrophic factor)
Diseases named in the same sentence as BDNF in open-access papers (continued):
Sharing a sentence is not in itself a finding about the gene and the disease.
Autoimmunity (6 papers, 2017 to 2023). The occurrence of an immune reaction against the organism's own cells or tissues. "Many ‘autoimmune’ disorders show upregulated TrkB-T1 and/or a dependence of cells or immune processes on BDNF." (PMID 37174637, 2023). "As of now, multiple aspects of interactions between BDNF, sleep, and autoimmunity, e.g., the influence of inflammation or sex on the circadian rhythmicity of BDNF production, remain elusive." (PMID 36294343, 2022). "We found that hAFSCs have the capability to produce brain‐derived neurotrophic factor and possessed anti‐autoimmunity and anti‐inflammatory functions." (PMID 34622573, 2021). "Our study demonstrated that hAFSCs had the capability to produce BDNF and possessed anti-autoimmunity and anti-inflammatory functions." (PMID 32572272, 2020). "Thus, a neuroprotective effect of BDNF/TrkB signaling in an immune-dependent demyelinated setting, such as in EAE, supports the concept of neuroprotective autoimmunity." (PMID 34070622, 2021). "The results demonstrated the colocalization of DAPI and hCD90 with the expression of BDNF, TGF-β1, GFAP, and interleukin-6 (IL-6) in hAFSCs, indicating that hAFSCs could produce neurotrophic factors and possess anti-autoimmunity and anti-inflammatory effects." (PMID 32572272, 2020).
bipolar II disorder (6 papers, 2016 to 2024). A bipolar disorder that is characterized by at least one hypomanic episode and at least one major depressive episode; with this disorder, depressive episodes are more frequent and more intense than manic episodes. "Interestingly, DRD3 Ser9Gly has been described as interacting with BDNF Val66Met in the development of anxiety disorder comorbidity in patients with bipolar disorder II." (PMID 33643008, 2021).
cardiac hypertrophy (6 papers, 2017 to 2025). "To exclude the cardiac amyloidosis as a potential cause for the cardiac hypertrophy that we observed in our Trp53inp2-cKO mice, we further evaluated BDNF, a marker for cardiac amyloidosis." (PMID 38188257, 2023). "•Animals with low (Dlow) but not high (Dhigh) BDNF levels present a cardiac hypertrophy and low parasympathetic activity." (PMID 33344701, 2020). "These animals were characterized by permanent low BDNF levels and presented not only with vagal reduction (modified indices of frequential HRV, spontaneous and pharmacological baroreflex responses), but also with cardiac hypertrophy, compared to the other defeated animals (Dhigh)." (PMID 33344701, 2020).
central obesity (6 papers, 2013 to 2025). "We firstly identified the genetic predisposition (BDNF SNPs) to general and central obesity in former smokers, particularly in former heavy smokers." (PMID 34525971, 2021). "Similar results were found for the association of rs6265 with central obesity and for the associations of other two BDNF SNPs (rs4923457 and rs11030104) with both general and central obesity." (PMID 34525971, 2021). "Our study presents the new evidence that FTO rs9939609, MC4R rs17782313, GNPDA2 rs10938397 and BDNF rs6265 are statistically significantly associated with risk of central obesity in the Chinese children." (PMID 23424664, 2013). "Our study replicates the statistically significant association of four SNPs (FTO rs9939609, MC4R rs17782313, GNPDA2 rs10938397, BDNF rs6265) with risk of central obesity in the Chinese children." (PMID 23424664, 2013). "The joint effect of four strongly associated SNPs (FTO rs9939609, MC4R rs17782313, GNPDA2 rs10938397, BDNF rs6265) on the risk of central obesity was further investigated." (PMID 23424664, 2013). "In conclusion, our study confirmed the significant association of four SNPs (FTO rs9939609, MC4R rs17782313, GNPDA2 rs10938397, BDNF rs6265) with risk of central obesity in the Chinese children." (PMID 23424664, 2013). "Additionally, the BDNF-rs7934165-AA genotype has been linked to a higher waist-to-height ratio, suggesting its potential utility as a biomarker for central obesity and cardiometabolic risk." (PMID 40697550, 2025). "We hypothesized that SNPs on BDNF are the genetic factors of general or central obesity associated with smoking cessation." (PMID 34525971, 2021). "Furthermore, our LD analysis to verify the association of each base combination on general and central obesity showed that the association of SNPs on BDNF in former smokers with general and central obesity varied by cigarette consumption and nicotine dependence before smoking cessation." (PMID 34525971, 2021). "The results indicated that four SNPs (FTO rs9939609, MC4R rs17782313, GNPDA2 rs10938397, BDNF rs6265) and GRS calculated from these 4 SNPs significantly predicted the risk of central obesity." (PMID 23424664, 2013).
coronary atherosclerosis (6 papers, 2010 to 2024). Atherosclerosis of the coronary vasculature. "The fact that plasma BDNF levels are significantly reduced in the chronic, advanced and acute stages of coronary atherosclerosis points to a potential role of a deficit of this neurotrophin in atherosclerosis pathogenesis." (PMID 20181009, 2010). "BDNF was also reported play an important role in coronary atherosclerosis development." (PMID 31010436, 2019). "We do not know why the level BDNF appears to be significantly depleted in humans with coronary atherosclerosis." (PMID 20181009, 2010).
demyelinating disease (6 papers, 2017 to 2025). A broad group of disorders that affect the myelin sheaths that cover the neurons. "In demyelinating disease models, NT-3 and BDNF have been linked to less severe phenotypes." (PMID 31105589, 2019). "Progress in the development of small molecule TrkB agonists offers hope that BDNF signalling can be harnessed for therapeutic benefit in human CNS demyelinating diseases." (PMID 30572673, 2018). "It remains to be confirmed whether activation of mGluR5 on human astrocytes may lead to secretion of BDNF as the case in mice and lead to a therapy for demyelinating disease." (PMID 41044782, 2025). "If in this second phase the beneficial effects are also confirmed, it can be hypothesized that BDNF may in the future be a useful agent for modulating a damaged brain environment to improve recovery during demyelinating diseases and possibly other degenerative conditions." (PMID 32397504, 2020).
intrauterine growth restriction (6 papers, 2021 to 2026). "Prematurity, placental dysfunction and fetal growth restriction have all been associated with reduced levels of BDNF which may have important implications for long-term brain health." (PMID 34512648, 2021). "Similarly, we found that fetal growth restriction is significantly associated with low BDNF levels." (PMID 37583548, 2023). "PND resulted in significant fetal growth restriction, decreased placental efficiency, and marked reductions in placental BDNF and VEGF." (PMID 42100781, 2026). "BDNF production alterations were also shown in intrauterine growth restriction, gestational diabetes, acute respiratory problems of the neonate, and ischemic neonatal brain injury." (PMID 37583548, 2023). "The largest study to date, related low levels of BDNF in dry blood tests (blood spots) taken on the first day of life in newborns with intrauterine growth restriction." (PMID 35208502, 2022). "Moreover, it is also conspicuous that fetal growth restriction is significantly related to low maternal and fetal cord BDNF levels according to the results of our study." (PMID 37583548, 2023). "Deficiencies in maternal brain-derived neurotrophic factor (BDNF) during pregnancy have been linked with gestational abnormalities, such as intrauterine growth restriction, preterm birth, and low birth weight, all of which could pose significant long-term impacts." (PMID 40310038, 2025).
lung adenocarcinoma (6 papers, 2014 to 2025). A carcinoma that arises from the lung and is characterized by the presence of malignant glandular epithelial cells. "Furthermore, patients with increased BDNF levels in primary lung adenocarcinoma might have a higher risk of developing brain metastasis, and central nervous system metastasis showed an elevated expression of BDNF compared to their matched primary lesions." (PMID 40654575, 2025). "Squamous cell carcinoma and adenocarcinoma of the lung express more elevated levels of BDNF at both protein and mRNA levels." (PMID 36289793, 2022). "We show here that forced expression of the TrkB receptor kinase in two human lung adenocarcinoma cell lines, A549 and NCI-H441, caused enhanced migratory capacity in the presence of the TrkB ligand BDNF." (PMID 24959744, 2014). "To identify relevant published data on NTs and NT receptors in lung adenocarcinoma, we conducted a literature search on PubMed using the following keywords: neurotrophins, NT receptors, nerve growth factor, Brain-Derived Neurotrophic Factor, NT-3, lung adenocarcinoma, and human”." (PMID 36289793, 2022). "Moreover, in in vitro lung adenocarcinoma cell culture, BDNF stimulates the pro-survival pathway via AKT suppressed by TrkB receptor inhibitor." (PMID 36289793, 2022).
lung diseases (6 papers, 2012 to 2024). "Neurotrophins like BDNF have been implicated in many lung diseases." (PMID 25003466, 2014). "Particularly, BDNF has been extensively studied as the neurotrophic factor with a major role in nervous and pulmonary diseases." (PMID 37108250, 2023). "In addition to its notable role in the nervous system, BDNF, as well as their receptors, are expressed in the lung crucially contributing to both normal physiology and pathophysiology of several pulmonary diseases." (PMID 39403060, 2024). "Because of the mentioned studies claiming the potential interaction between ischemic processes, lung diseases, and BDNF levels, we hypothesized that BDNF levels might have deteriorated in cases complicated with MSAF when the fetus is under distress due to possible hypoxic events." (PMID 37583548, 2023). "It was proven to play a contribution in airway obstruction and hyperresponsiveness in a model of allergic asthma, and elevated BDNF levels in the serum of patients with COPD were found at all stages, further indicating a role of this molecule in the pathogenesis of diverse pulmonary diseases." (PMID 39403060, 2024).
lung fibrosis (6 papers, 2017 to 2025). "Histological analysis assessed pulmonary fibrosis, and biomarkers brain-derived neurotrophic factor (BDNF) and c-Fos were detected." (PMID 40655156, 2025). "Activation of the BDNF/TrkB axis accelerated epithelial–mesenchymal transition in idiopathic pulmonary fibrosis." (PMID 33477900, 2021). "For example, Cherubini and colleagues found that TrkB was expressed in lung fibroblasts, and activation of BDNF/TrkB axis promoted the epithelial–mesenchymal transition in idiopathic pulmonary fibrosis." (PMID 33477900, 2021). "Targeting BDNF/TrkB seems to represent a viable approach in order to prevent EMT dependent lung fibrosis." (PMID 28938915, 2017). "Targeting BDNF/TrkB is a feasible method to prevent EMT-dependent pulmonary fibrosis." (PMID 34646338, 2021). "Therefore, BDNF represents an attractive molecule able to participate to the complex pro-fibro-genetic cytokine network that participate to lung fibrosis in IPF." (PMID 28938915, 2017). "However, apart from these limited results there is no clear data about the biological role the BDNF/TrkB signaling pathway in idiopathic pulmonary fibrosis." (PMID 28938915, 2017).
opioid dependence (6 papers, 2015 to 2022). "Evidence that BDNF mediates the impaired DA signaling in opioid dependence includes injection of BDNF into the VTA, which mimicked an opioid-dependent reward-like state." (PMID 26202104, 2016). "Likewise, upregulation of BDNF and NT-3 occurs in the brain regions that are involved in opioid dependence and withdrawal following repeated morphine treatment." (PMID 27596139, 2016). "Some studies have suggested that changes in proinflammatory cytokines and BDNF may be related to the pathophysiology of opioid dependence." (PMID 25716777, 2015). "Other studies have also indicated that brain-derived neurotrophic factor (BDNF), as well as its receptor, tropomyosin receptor kinase B (TrkB), may also play integral roles in opioid dependence and withdrawal development." (PMID 36532632, 2022).
periodontal disease (6 papers, 2014 to 2026). "In conclusion, BDNF seems to be associated with periodontal disease process, but the specific role of BDNF still needs to be clarified." (PMID 25587209, 2014). "We hypothesise that both Vitamin D deficiency and altered BDNF expression may serve as key biomarkerslinking periodontal disease to neuropsychiatric conditions, adding to the growing body of evidence on the systemic impact ofperiodontitis." (PMID 40822814, 2025). "Recently, BDNF has been considered as a potential therapeutic for some neurogenic disorders and periodontal diseases." (PMID 28072837, 2017). "The presentstudy adds to the emerging evidence on the role of BDNF in neuropsychiatric disorders and periodontal diseases.Our findings revealed that BDNF levels were significantly reduced in participants with neuropsychiatric disorders, regardless ofperiodontal health (p = 0.01)." (PMID 40822814, 2025). "Previously, two studies have evaluated the effects of BDNF polymorphisms in bone, but there are no available studies in periodontal disease." (PMID 25587209, 2014). "Although a role for BDNF in periodontal regeneration has been suggested, a function for BDNF in periodontal disease has not yet been studied." (PMID 25587209, 2014). "Although a role for BDNF in periodontal regeneration has been proposed, no information is available concerning BDNF and periodontal disease." (PMID 25587209, 2014).
personality disorder (6 papers, 2014 to 2024). A diverse category of psychiatric disorders characterized by behavior that deviates markedly from the expectations of the individual's culture; this pattern of deviation is pervasive and inflexible and is stable over time. "Brain-derived neurotrophic factor (BDNF) has previously been associated with the pathogenesis of both emotionally unstable personality disorder (EUPD) and suicidal behavior." (PMID 36766691, 2023).
prostatitis (6 papers, 2019 to 2025). An infectious or non-infectious inflammatory process affecting the prostate gland. "BDNF-positive neurons associated with the expression of Trk-A immunoreactivity were increased in the prostatitis groups, whose effects were attenuated by 200 and 300 shocks of Li-ESWT." (PMID 35563108, 2022). "The protein levels of TRPV1 and BDNF in the L6 DRG/spinal cord were increased in capsaicin-induced prostatitis rats and were downregulated by Li-ESWT." (PMID 35563108, 2022). "Previous reports have found that the levels of some molecules associated with pain conditions, including CCL3, IL-1B, TNF-α, brain-derived neurotrophic factor (BDNF), and substance P, are increased in the spinal cord of prostatitis animal models." (PMID 31653262, 2019).
relapsing-remitting MS (6 papers, 2013 to 2025). "BDNF levels are lower in relapsing-remitting MS (RRMS) patients than in healthy controls, and levels of BDNF correlate with EDSS scores of RRMS patients." (PMID 41234467, 2025). "For example, several studies have shown that fingolimod, the first approved oral drug for MS, glatiramer acetate and laquinimod exert their beneficial effect in treating relapsing remitting MS (RRMS) by increasing BDNF levels." (PMID 28604632, 2017). "Similarly, a significant elevation of serum BDNF levels in relapse remitting MS (RRMS) patients receiving LQ therapy was observed." (PMID 24363970, 2013).
schizoaffective disorder (6 papers, 2016 to 2024). "With respect to schizoaffective disorder, it has been reported in the literature that there is a lower serum BDNF level with respect to control subjects in a similar proportion to patients with SCZ." (PMID 39456983, 2024).
triple-negative breast carcinoma (6 papers, 2017 to 2022). An invasive breast carcinoma which is negative for expression of estrogen receptor (ER), progesterone receptor (PR), and human epidermal growth factor receptor 2 (HER2). "Our previous study demonstrated that an up-regulation of the Brain-Derived Neurotrophic Factor (BDNF) signaling pathway is involved the mechanism causing the recurrence of triple negative breast cancer." (PMID 28800782, 2017). "Our study demonstrates that up-regulation of the BDNF signaling pathway seems tobe involved in the mechanism associated with early recurrence in triple negative breast cancer cell." (PMID 28604807, 2017). "In triple-negative breast cancer, the interaction of estradiol with BDNF and its receptor, promotes brain metastasis." (PMID 32971738, 2020). "In triple-negative breast cancer, BDNF promotes cancer progression via activating TrkB." (PMID 33942699, 2021). "In the Triple-Negative Breast Cancer (TNBC) brain metastasis model, BDNF was shown to autocrine regulate the expression of the BDNF-tumor cell trophic carnosine kinase receptor B (TrkB) gene, thereby increasing the migration activity of cells." (PMID 36406133, 2022).
acne vulgaris (5 papers, 2019 to 2023). "We conducted the present systematic review and meta-analysis to elucidate the association of acne vulgaris with psychiatric comorbidities and quality of life as well as the brain‐derived neurotrophic factor (BDNF) level." (PMID 36751189, 2023). "Serum BDNF levels were decreased and negatively associated with depressive symptoms in young Chinese adults with acne vulgaris." (PMID 31234814, 2019). "The study aimed to determine the potential association between BDNF and depressive symptoms in young adults with acne vulgaris." (PMID 31234814, 2019). "Our results demonstrate that the serum BDNF levels were negatively associated with depressive symptoms in young Chinese adults with acne vulgaris." (PMID 31234814, 2019). "Our results showed that levels of BDNF expression were lower in consecutive acne vulgaris patients when compared with healthy control (P < 0.05)." (PMID 31234814, 2019). "Summarized data from all individuals showed that the quantity of serum levels of BDNF in acne vulgaris patients were significantly lower than that in healthy controls (13.35 ± 2.65 vs. 14.35 ± 2.70; P = 0.038)." (PMID 31234814, 2019). "Consistent with previous studies, in our research, acne vulgaris patients showed lower serum BDNF levels compared with healthy controls." (PMID 31234814, 2019). "With reference to BDNF evaluation, although the score can be used as an indicator of mental stress, there is still a lack of evidence to conclude that it can be used as a specific indicator for evaluating the mental stress of acne vulgaris patients." (PMID 36751189, 2023). "Moreover, they revealed that the concentration of BDNF in patients with severe acne was notably lower compared to its concentration in patients with mild cases." (PMID 36751189, 2023). "Furthermore, we planned to document the evidence for the use of BDNF as a scarring biomarker to predict other clinical pathological feature outcomes of acne vulgaris." (PMID 31234814, 2019). "Thus, understanding the mechanisms of BDNF has considered as a promising scarring approaches of the acne vulgaris therapy." (PMID 31234814, 2019). "In this context, we carry out a systematic review and meta-analysis study in order to assess psychiatric comorbidities and quality of life, as well as brain-derived neurotrophic factor (BDNF) level, in patients suffering from acne vulgaris." (PMID 36751189, 2023). "But, there is no report of serum BDNF levels in patients with acne vulgaris." (PMID 31234814, 2019). "Our results clearly show a negative correlation between serum levels of BDNF and PHQ-9 score in acne vulgaris patients (r = − 0.486, P < 0.001)." (PMID 31234814, 2019).